SLC5A12 (solute carrier family 5 member 12)
Description:
Acts as an electroneutral and low-affinity sodium Na(+)- dependent sodium-coupled solute transporter. Catalyzes the transport across the plasma membrane of many monocarboxylates such as lactate, pyruvate, nicotinate, propionate, butyrate and beta-D-hydroxybutyrate (By similarity). May be responsible for the first step of reabsorption of monocarboxylates from the lumen of the proximal tubule of the kidney and the small intestine. May play also a role in monocarboxylates transport in the retina (By similarity). Probably part of D-serine transport systems involved in D-serine reabsorption at the brush border of renal proximal tubules.
Synonyms: SMCT2; MGC52019
Tractability: Antibody: UniProt places it where antibodies can reach, with high confidence; its Gene Ontology location is reachable by antibodies, with high confidence; UniProt predicts a signal peptide or a membrane-spanning region; the Human Protein Atlas places it where antibodies can reach.
Gene: Protein-coding gene on chromosome 11 (26,667,020 to 26,723,427, reverse strand). Ensembl gene ENSG00000148942.
Subcellular location: Apical cell membrane
Subcellular location (Human Protein Atlas): Plasma membrane; Nucleoplasm
Pathways (Reactome):
Transport of small molecules: Organic anion transport by SLC5/17/25 transporters
Gene Ontology:
Molecular function: protein binding; lactate transmembrane transporter activity; monocarboxylate:sodium symporter activity; organic acid:sodium symporter activity; solute:sodium symporter activity; transmembrane transporter activity
Biological process: monocarboxylic acid transport; sodium ion transport; transmembrane transport; lactate transmembrane transport; sodium ion transmembrane transport
Cellular component: apical plasma membrane; extracellular exosome; plasma membrane; membrane
Genetic constraint (gnomAD): Loss-of-function variants: 32 observed, 55.55 expected, observed/expected ratio (o/e) 0.58, 90% interval 0.43 to 0.77. The upper end of that interval is the gene's LOEUF score, 0.77, which puts it in group 3 of 6, group 1 being the genes least tolerant of losing a copy. Missense variants: 584 observed, 645.32 expected, observed/expected ratio (o/e) 0.9, 90% interval 0.85 to 0.97. Synonymous variants: 236 observed, 235.6 expected, observed/expected ratio (o/e) 1, 90% interval 0.9 to 1.12.
Homologues: Orthologues: chimpanzee SLC5A12 (99% identical), macaque SLC5A12 (96% identical), dog SLC5A12 (90% identical), pig SLC5A12 (89% identical), rabbit SLC5A12 (87% identical), mouse Slc5a12 (86% identical), guinea pig SLC5A12 (84% identical), rat Slc5a12 (84% identical), tropical clawed frog slc5a12 (73% identical), zebrafish slc5a12 (66% identical), Drosophila melanogaster bumpel (31% identical), Drosophila melanogaster kumpel (30% identical), and 10 more. Paralogues in human: SLC5A8 (52% identical), SLC5A5 (44% identical), SLC5A6 (41% identical), SLC5A11 (24% identical), SLC5A2 (23% identical), SLC5A9 (22% identical), SLC5A1 (22% identical), SLC5A4 (22% identical), SLC5A3 (21% identical), SLC5A10 (21% identical), SLC5A7 (18% identical).
Diseases named in the same sentence as SLC5A12 in open-access papers:
SLC5A12 is named in the same sentence as 16 diseases in open-access papers, as found by Europe PMC text mining. Sharing a sentence is not in itself a finding about the gene and the disease. The quoted sentences say what the papers report.
Arthritis (3 papers, 2020 to 2024). Inflammation of a joint. "Monoclonal antibodies against SLC5A12 were successfully used to treat murine model of arthritis, and SLC5A12 is a potential target for future human trials for RA and other inflammatory arthritis." (PMID 32341806, 2020). "Furthermore, SLC5A12 antibody blockade led to amelioration in the severity of arthritis in a murine model of arthritis." (PMID 35020864, 2022).
rheumatoid arthritis (3 papers, 2020 to 2024). A chronic, systemic autoimmune disorder characterized by inflammation in the synovial membranes and articular surfaces. "Consistently, inhibiting lactate transporter SLC5A12 ameliorates disease severity in a murine model of rheumatoid arthritis (RA)." (PMID 38275212, 2024). "Recently, it has been found that lactate uptake via SLC5A12 results in pyruvate kinase M2/signal transducer and activator of transcription 3 (PKM2/STAT3)-mediated production of IL-17 in CD4+ T cells in rheumatoid arthritis (RA)." (PMID 33086598, 2020).
autoimmune disease (1 paper, 2025). A disorder resulting from loss of function or tissue destruction of an organ or multiple organs, arising from humoral or cellular immune responses of the individual to their own tissue constituents. "Therefore, SLC5A12 blockade shows multidimensional beneficial effects which are reminiscent of blockade of PD1 and CTLA4 in immuno-oncology, leading us to propose that SLC5A12 represents an important example of a checkpoint in inflamed tissues in autoimmune diseases." (PMID 40759752, 2025).
head and neck squamous cell carcinoma (1 paper, 2022). A squamous cell carcinoma that arises from any of the following anatomic sites: lip and oral cavity, nasal cavity, paranasal sinuses, pharynx, larynx, and salivary glands. "However, a recent study found that SLC5A12 is a prognostic marker in head and neck squamous cell carcinoma." (PMID 35634240, 2022).
ischemia (1 paper, 2021). A hypoperfusion of the BLOOD through an organ or tissue caused by a PATHOLOGIC CONSTRICTION or obstruction of its BLOOD VESSELS, or an absence of BLOOD CIRCULATION. "After accounting for multiple testing, we found only one gene to be significantly regulated by anaesthesia during ischemia-reperfusion injury: slc5a12 (sodium/glucose cotransporter, 71-fold decrease in ischemia with anaesthesia compared to conscious ischemia, FDR = 0.03)." (PMID 34576005, 2021).
Obesity (1 paper, 2022). Accumulation of substantial excess body fat. "The mEC1 population showed an obesity-induced downregulation of transporters of major ions (Slc34a1, Slc4a4, Slc22a8, Slc13a1, Slc22a18 and Slc5a12), neutral amino acids (Slc6a19) and glucose (Slc5a2)." (PMID 36400935, 2022).
Sepsis (1 paper, 2022). Sepsis is defined as life-threatening organ dysfunction caused by a dysregulated host response to infection. "Our findings revealed three novel low-frequency variants associated with reduced 28-day survival among sepsis patients: one in SAMD9 (the p.Ala1556Thr exonic variant), one intergenic to SLC5A12\FIBIN, and another intergenic to LINC00378\MIR3169." (PMID 36335405, 2022).
sialadenitis (1 paper, 2025). Sialadenitis is an infection of the salivary glands. "We next evaluated the formation and function of inflammatory infiltrates and ELS through the genetic or pharmacological blockade of SLC5A12 in the viral-induced murine model of sialadenitis, which mimics focal lymphocytic aggregation and ELS in SjD." (PMID 40759752, 2025).
squamous cell carcinoma (1 paper, 2022). A carcinoma arising from squamous epithelial cells.
tumor (4 papers, 2016 to 2023). "Another validated focal CNA detected in one tumor (WT201) was the 825 kb homozygous deletion at 11p14.1p14.2 (#chr11:26,688,179-27,513,817; GRCh37), harbouring BBOX, among others genes (SLC5A12, FIBIN, CCDC34, LGR4)." (PMID 26913079, 2016).
cancer (1 paper, 2014). A tumor composed of atypical neoplastic, often pleomorphic cells that invade other tissues. "SLC5A8 and SLC5A12 transporters mediate uptake of a variety of monocarboxylates including benzoic acid and show different concentration profiles in normal vs. cancer tissues." (PMID 24954394, 2014).
SLC5A12 also shares sentences with these, for which no sentence is quoted: colitis (2 papers); acute kidney injury (1); adenocarcinoma (1); Autoimmunity (1); morbid obesity (1).